CCL28 (C-C motif chemokine ligand 28)
Description:
Chemotactic activity for resting CD4, CD8 T-cells and eosinophils. Binds to CCR3 and CCR10 and induces calcium mobilization in a dose-dependent manner.
Synonyms: MEC; SCYA28; CCK1
Tractability: Antibody: its Gene Ontology location is reachable by antibodies, with high confidence; UniProt places it where antibodies can reach, with medium confidence; UniProt predicts a signal peptide or a membrane-spanning region.
Gene: Protein-coding gene on chromosome 5 (43,376,645 to 43,412,391, reverse strand). Ensembl gene ENSG00000151882.
Subcellular location: Secreted
Pathways (Reactome):
Signal Transduction: Chemokine receptors bind chemokines; G alpha (i) signalling events
Gene Ontology:
Molecular function: chemokine activity; protein binding; CXCR chemokine receptor binding; chemokine receptor binding
Biological process: cell chemotaxis; negative regulation of leukocyte tethering or rolling; positive regulation of cell-matrix adhesion; antimicrobial humoral immune response mediated by antimicrobial peptide; cellular response to lipopolysaccharide; chemotaxis; inflammatory response; neutrophil chemotaxis; immune response; response to nutrient
Cellular component: extracellular exosome; extracellular region
Genetic constraint (gnomAD): Loss-of-function variants: 5 observed, 8.48 expected, observed/expected ratio (o/e) 0.59, 90% interval 0.31 to 1.24. That is too few expected variants to judge how well the gene tolerates losing a copy. Missense variants: 151 observed, 172.48 expected, observed/expected ratio (o/e) 0.88, 90% interval 0.77 to 1. Synonymous variants: 55 observed, 60.76 expected, observed/expected ratio (o/e) 0.91, 90% interval 0.73 to 1.13.
Homologues: Orthologues: chimpanzee CCL28 (100% identical), macaque CCL28 (96% identical), dog CCL28 (78% identical), pig CCL28 (76% identical), rat Ccl28 (67% identical), mouse Ccl28 (63% identical), zebrafish ccl27a (23% identical), zebrafish ccl27b (18% identical). Paralogues in human: CCL27 (26% identical).
Diseases named in the same sentence as CCL28 in open-access papers:
CCL28 is named in the same sentence as 118 diseases in open-access papers, as found by Europe PMC text mining. Sharing a sentence is not in itself a finding about the gene and the disease. The quoted sentences say what the papers report.
ovarian carcinoma (14 papers, 2012 to 2025). A malignant neoplasm originating from the surface ovarian epithelium. "Apart from its chemotactic properties, CCL28 has been implicated in promoting tumor development in ovarian cancer, gastric cancer, liver cancer, and lung adenocarcinoma." (PMID 39075504, 2024). "Another chemokine, CCL28 (mucosae associated epithelial chemokine) is also upregulated by hypoxia and HIF-1α in human ovarian cancer cell lines." (PMID 40852716, 2025). "In ovarian cancer, the overexpression of CCL28 promotes the recruitment, to the tumor site, of the Treg cells, through their CCR10 receptor." (PMID 33066172, 2020). "Further, tumor-associated hypoxia enhances Treg cell infiltration and accumulation via chemotactic factors, such as C-C motif chemokine ligand 28 (CCL28), promoting tumor tolerance and angiogenesis in ovarian cancer." (PMID 31535086, 2019). "Notably, hypoxia induces the expression of CCL28 in ovarian cancer, which, in turn, enhances angiogenesis by recruiting regulatory T cells (Tregs)." (PMID 39075504, 2024). "Notably, neutralising CCL28 with an antibody decreases Treg cell infiltration and suppresses tumour growth, as has been shown in gastric and ovarian cancer." (PMID 37380804, 2023). "Hypoxia can increase the expression and secretion of CCL28 in ovarian cancer cells." (PMID 33344235, 2020). "Frequencies of CCR10-expressing CD39+ Treg were however dramatically lower in the tumor compared to peripheral blood, even though recent findings in human ovarian cancer cell lines show that hypoxia induces CC-chemokine ligand 28 (CCL28) which in turn recruits CCR10-expressing Treg." (PMID 30651930, 2018). "Moreover, a previous study has reported that CCL28 could recruit Tregs and promote angiogenesis in ovarian carcinoma." (PMID 39075504, 2024). "Hypoxia promotes the expression of CCL28, resulting in abnormal accumulation of Tregs via the CCL28-CCR10 pathway in ovarian cancer cells." (PMID 33413697, 2021). "The results revealed high expression of chemokines in the following ovarian cancer cell lines: CCL20 and 28, CXCL1, 2, 3 and 8 in OVCAR-3 cells; CCL28 and CXCL1 in SKOV-3 cells; CXCL1, 2 and 8 in CaOV-3 cells; and CXCL2 in TOV-21G cells." (PMID 23300534, 2012). "Previous studies in mouse or human ovarian cancers suggested that TI Tregs could be recruited from the circulation to tumors by CCL22 and CCL28." (PMID 28290464, 2017). "In fact, CCL28 level remained unchangeable in all human ovarian cancer cells tested (data not shown)." (PMID 23300534, 2012). "It is speculated that ovarian cancer cells promote the expression of CCL28 on the cell surface through the HIF signaling pathway during hypoxia, and CCL28 interacts with CCR10 on the surface of Tregs to recruit it by chemotaxis into the tumor tissue and exert immunosuppressive effects." (PMID 30477520, 2018). "The lack of induction of CCL28 by TNF in these ovarian cancer cells is in contrast to earlier report that TNF and IL-1 increase expression of CCL28 in human keratinocyte cells and colon epithelium." (PMID 23300534, 2012).
breast carcinoma (13 papers, 2017 to 2025). "Again, CCL28 levels in tumor tissue have a favorable prognostic role in luminal breast cancer but are associated with a worse prognosis in TNBC." (PMID 38594742, 2024). "For the next common core signaling pathway, the receptor ERBB2, which was mutated in breast cancer, received microenvironment factor CCL28 to activate TF BRCA1 through signaling transduction proteins CDC42 and ARRDC3 in TNBC and non-TNBC." (PMID 33802957, 2021). "CCL28 promotes breast cancer cell proliferation and metastasis through activation of the MAPK signaling pathway, upregulation of antiapoptotic protein Bcl-2, and inhibition of cell adhesion protein β-catenin." (PMID 35463082, 2022). "For this reason, chemokines such as CCL1/I-309 (in breast cancer), CCL17/TARC, CCL22/MDC (in gastric cancer and hepatocellular carcinoma), and CCL28/MEC (in hepatocellular carcinoma) cause Treg recruitment into the tumor niche." (PMID 33114763, 2020). "In patients with luminal-like breast cancer, elevated concentrations of CCL28 in the tumor improve prognosis, in contrast to triple-negative breast cancer." (PMID 33076281, 2020). "Significant changes in CCL22 and CCL28 in the online breast cancer data sets also showed decreased tumor expression, suggesting that these chemokines are unlikely to play an important role in Treg recruitment to breast cancer." (PMID 28290464, 2017). "Moreover, CCL28 has been shown to drive the growth and metastatic spread of breast cancer by activating the MAPK/ERK1/2 pathway, while the CXCL12-CXCR4 axis supports cancer cell proliferation, relying on the MAPK pathway for its effects." (PMID 39735670, 2025). "Based on their functions in biology and carcinogenesis, the current results imply that serum CCL8, CCL23 and CCL28 could also be drivers of aggressive breast cancer behavior in situ." (PMID 38594742, 2024). "For breast cancer, there is evidence that CCL28 and PHLPP1 may be drivers of breast cancer through the MAPK and AKT pathways, respectively." (PMID 39010058, 2024). "These include FAM183A, which is upregulated in breast cancer cells in response to Notch signaling; MUC4, expressed in 95% of breast carcinomas; HSPB6, which is downregulated in breast cancer; and CCL28, which promotes breast cancer proliferation, tumor growth and metastasis." (PMID 33957961, 2021). "Expression of CCL28 is down-regulated in breast cancer, colon cancer, and multiforme glioblastoma." (PMID 33076281, 2020). "Contrastingly, in breast cancer, CCL28 expression has a dual effect: in luminal-like subtypes, it correlates with improved relapse-free survival (RFS) and disease-free survival (DFS), while in triple-negative breast cancer (TNBC), high CCL28 expression is associated with poorer prognosis." (PMID 40508156, 2025). "We further demonstrated that plasma levels of CCL28 and IGFBP2 proteins were significantly higher in breast cancer patients during taxane-based chemotherapy than post-chemotherapy." (PMID 38093346, 2023). "The identified CCL proteins have various carcinogenetic properties, such as the increase in breast cancer cell proliferation, chemoresistance development and T-cell and NK-cell regulation (CCL8), stimulation of angiogenesis and cancer cell proliferation (CCL23) and control of cell migration (CCL28)." (PMID 38594742, 2024). "However, CCL22 and CCL28 expression is not increased in human breast cancers compared to normal breast tissue, making them unlikely Treg recruiters to human breast cancer." (PMID 28290464, 2017).
gastric cancer (11 papers, 2021 to 2025). A primary or metastatic malignant neoplasm involving the stomach. "The activation of the β‐catenin‐CCL28‐Tregs signaling axis is also closely associated with the immunosuppressive TME in gastric cancer." (PMID 37666495, 2024). "Activation of β-linked protein in gastric cancer leads to upregulation of CCL28 expression and subsequent recruitment of Treg cells thereby inhibiting gastric cancer progression." (PMID 36890467, 2023). "In gastric cancer, β-catenin upregulates CCL28, enhancing Treg recruitment, blocking CCL28 reduces Treg infiltration and tumor growth." (PMID 41050670, 2025). "CCL28 was identified as a β-catenin target gene in gastric cancer cells, and blocking the β-catenin/CCL28 axis suppresses Treg cell infiltration and gastric cancer progression." (PMID 36765047, 2023). "NR3C2, SYNPO2, and CCL28, three genes targeted by mir-21, were shown to be highly expressed in both stomach cancer and healthy tissues." (PMID 38081950, 2023). "The examination of quantitative polymerase chain reaction (qPCR) data demonstrated a substantial downregulation (p value < 0.0001) in the expression of SYNPO2, NR3C2, and CCL28 in gastric cancer tissue samples when compared to matched tumour margin samples." (PMID 38081950, 2023). "Quantitative polymerase chain reaction (qPCR) was used to examine the expression levels of SYNPO2, NR3C2, and CCL28 in a total of 24 gastric cancer samples and 24 margin samples." (PMID 38081950, 2023). "The results demonstrated that the knockdown of DNAAF3 led to a decrease in the expression of β-Catenin and its downstream target CCL28 in gastric cancer, resulting in the suppression of Treg cell (FOXP3+) infiltration." (PMID 37711621, 2023). "Our study presents evidence suggesting that DNAAF3 may play a positive regulatory role in the activation of Treg cells induced by gastric cancer through the β-Catenin-induced CCL28 pathway." (PMID 37711621, 2023). "In addition, CCL28 is upregulated in multiple malignancies, including NSCLC and pancreatic cancer and blockade of CCL28 suppresses gastric cancer progression." (PMID 39632285, 2024).
colorectal cancer (10 papers, 2016 to 2025). A primary or metastatic malignant neoplasm that affects the colon or rectum. "The chemokine CCL28 was overexpressed in colorectal cancer and associated with poor prognosis." (PMID 33868236, 2021). "For instance, while LCA activation of TGR5 induced cytostatic oxidative stress in breast cancer cells, SBA activation of TGR5 on colorectal cancer cells promoted Treg recruitment via β-catenin/CCL28 signaling, facilitating immune evasion." (PMID 40821794, 2025). "In colorectal cancer, epithelial STAT3 loss increases CCL28, enhancing Treg migration, while CCL27-driven Th22 recruitment and IL-22 production, support tumor progression." (PMID 41050670, 2025). "Further analysis showed that differentially expressed genes such as PPBP, CCL28, and CXCL12 are likely to be involved in the development of colorectal cancer and may be potential diagnostic and therapeutic targets." (PMID 32797167, 2020). "Based on TCGA data, there was a positive correlation between CCL28 and KRAS expressions in PDAC and colorectal carcinomas." (PMID 37380804, 2023). "For instance, in colorectal cancer (CRC), microbially produced secondary BAs like deoxycholic acid (DCA) and LCA can activate TGR5 on tumor cells, leading to CCL28-mediated recruitment of immunosuppressive Tregs into the tumor, thereby fostering tumor progression." (PMID 40821794, 2025). "(2023) showed that bile salt hydrolase (BSH) activity in non-enterotoxigenic Bacteroides potentiated colorectal cancer (CRC) by increasing colonic deoxycholic acid (DCA) and lithocholic acid (LCA), which activated tumor cell TGR5, upregulated CCL28, and promoted immunosuppressive Treg infiltration." (PMID 40821794, 2025).
hepatocellular carcinoma (7 papers, 2016 to 2025). A malignant tumor that arises from hepatocytes. "A recent study showed that in hypoxia hepatocellular carcinoma cells, CCL28 was demonstrated to be responsible for recruitment of Tregs and eventually resulted in tumor growth in liver cancer." (PMID 30216450, 2019). "We first examined if hypoxia-induced CCL28 upregulation also work in a mouse hepatoma cell line (Hepa1-6), results showed hypoxia induced an increase of CCL28 expression." (PMID 27716621, 2016). "It has been suggested that CCL28 is up-regulated in HCC and can promote the recruitment of regulatory T cells and the invasion and migration of hepatocellular carcinoma." (PMID 37400985, 2023). "In hepatocellular carcinoma (HCC) cells, hypoxia is related to immunosuppressive Tregs recruitment through induction of C–C motif chemokine ligand 28 (CCL28) expression." (PMID 35659268, 2022). "In this study, we found that hypoxia hepatocellular carcinoma (HCC) cells recruited Regulatory T cells (Tregs) and expressed more Chemokine (C-C motif) ligand 28 (CCL28)." (PMID 27716621, 2016). "Chemokines secreted by hepatoma cells, such as CCL5, CCL22, and CCL28, increase the infiltration of those Tregs, leading to the impaired activity of antigen-presenting cells (APCs) and immune cells in TME." (PMID 35965575, 2022). "Chronic hypoxia increases CCL28/MEC expression, as shown in cervical cancer cells, hepatocellular carcinoma, lung adenocarcinoma, melanoma cells, and ovarian cancer." (PMID 32781743, 2020). "For instance, Tregs, which abundantly express CCR4, CCR8 and CCR10, were directed to hepatocellular carcinoma (HCC) sites, where their corresponding ligands, CCL22 and CCL28, were present, affecting the treatment outcome by evading the immune system." (PMID 40852716, 2025).
influenza (6 papers, 2011 to 2025). An acute viral infection of the respiratory tract, occurring in isolated cases, in epidemics, or in pandemics; it is caused by serologically different strains of viruses (influenzaviruses) designated A, B, and C, has a 3-day incubation period, and usually lasts for 3 to 10 days. "A vaccination strategy that employs the intramuscular co-delivery of CCL27 or CCL28 has been shown to generate strong systemic and local immune responses, leading to the production of long-lived antibodies that neutralize influenza." (PMID 41194927, 2025). "Both CCL27 and CCL28 have also been shown to provide immunity against influenza and HIV due to the fact that adjuvant activity is dependent on CCR10-expressing plasma B cells that produce IgA and accumulate at mucosal surfaces." (PMID 40975172, 2025). "Because of its specific role in orchestrating the localization of IgA ASCs at mucosal sites, we previously analyzed the adjuvanticity of GPI-anchored CCL28 co-incorporated into influenza VLPs." (PMID 28067290, 2017). "In the current study, we demonstrated that influenza VLP vaccines containing GPI-anchored CCL28 induced long-lasting protective immunity against infection with either homologous or heterologous H3N2 viruses." (PMID 28067290, 2017). "Furthermore, studies have shown that the addition of a CCL28 adjuvant in H3N2 influenza vaccines can induce a significant increase in IgA levels and hemagglutination inhibition (HI) titers, enhancing long-term cross-protection against H3N2 influenza virus." (PMID 41194927, 2025). "When used as a virus-like particle (VLP) vaccine adjuvant for influenza vaccines, CCL28 can act as an immune stimulant in a membrane-bound form, eliciting a systemic mucosal immune response and significantly enhancing the host’s cross-protective efficacy against heterologous viruses." (PMID 41194927, 2025). "In addition to this, CCL28 has been used in influenza vaccines where CCL28 was adjuvanted with influenza virus-like particles and intranasally administrated into mice." (PMID 35891284, 2022). "Our lab has previously demonstrated that GPI-anchored CCL28 (GPI-CCL28) acted as an effective adjuvant in an influenza VLP vaccine, which induced robust immune responses at systemic and mucosal compartments and provided significant cross-protection against heterologous viral infection." (PMID 33430259, 2021). "As our vaccine composition contains influenza HA and GPI-anchored CCL28 co-incorporated into the same cVLP, which leads to the delivery of antigen and an immune stimulator to the same immune cells and may contribute a robust increase in the influenza specific immune responses in the cVLP group." (PMID 28067290, 2017). "Similarly, one-month post-vaccination, increased HAI titers were observed in the animal groups given influenza VLPs both with and without CCL28 groups, demonstrating protective immunity." (PMID 28067290, 2017).
asthma (5 papers, 2015 to 2024). "High CCL28 levels are present in airway biopsies from asthma patients, and CCR3+ and CCR10+ cells are recruited to the airways in a CCL28-dependent fashion in murine asthma models." (PMID 39193987, 2024). "Collectively, a variety of studies have postulated that CCL28 is an important chemokine in inflammatory diseases, ranging from asthma to ulcerative colitis, and during the immune response to infection." (PMID 39193987, 2024). "The receptor is then crosslinked by an antigen, the DCs produce the T cell chemoattractant chemokine ligand 28 (CCL28) and recruit IL-13-producing Th2 cells that can contribute to asthma." (PMID 34490286, 2021). "Taken together, this evidence suggests relevance for the CCR10/CCL28 axis in respiratory diseases and, in particular asthma." (PMID 26112287, 2015). "The involvement of CCL28 and its receptors CCR3 and CCR10 has been implicated in inflammatory lung diseases including asthma." (PMID 26112287, 2015). "CCL28 may also have a role in asthma pathogenesis with high levels of CCL28 in sputum and CCL28 receptors being expressed on eosinophils in patients with asthma and atopic disease." (PMID 38128411, 2024). "CCL28 was found elevated in the lungs of patients with asthma." (PMID 34490286, 2021).